LIFR (LIF receptor subunit alpha)
Diseases named in the same sentence as LIFR in open-access papers (continued):
Sharing a sentence is not in itself a finding about the gene and the disease.
ovarian carcinoma (4 papers, 2024 to 2025). A malignant neoplasm originating from the surface ovarian epithelium. "Recent studies indicate that the suppression of LIF/LIFR autocrine loops in ovarian cancer induces cell death by triggering ferroptosis through the downregulation of GPX4 levels." (PMID 40075639, 2025). "Autocrine or paracrine loops of LIF/LIFR have been identified in several cancers, such as pancreatic, lung, and ovarian cancer." (PMID 40075639, 2025). "Notably, we found that OSMR, LIFR, IL6R, and IL6ST mRNA were highly upregulated in cisplatin-resistant ovarian cancer cells in both A2780 and OVCAR8 cells." (PMID 38839865, 2024).
rhabdomyosarcoma (4 papers, 2015 to 2022). A rare aggressive malignant mesenchymal neoplasm arising from skeletal muscle. "In-vivo, targeting of the LIF/LIFR pathway through inhibition of LIFR with small interfering RNA was shown to inhibit metastasis in rhabdomyosarcoma xenografts, further highlighting both the role of LIF in tumourigenesis and therapeutic targeting potential of this pathway." (PMID 30263091, 2018). "Another cancer that typically metastasizes to bone is rhabdomyosarcoma, mouse models of rhabdomyosarcoma identified LIF expression within the bone marrow as a chemoattractant for rhabdomyosarcoma cells, and treatment with siRNA against LIFR was able to decrease bone metastasis." (PMID 35204717, 2022).
adenomyosis (3 papers, 2019 to 2025). The growth of endometrial tissue inside the muscular wall of the uterine corpus. "Recent evidence suggests the expression of leukemia inhibitory factor receptor (LIFR) affects multiple signaling pathways in the endometrium of patients with adenomyosis during the window of implantation for in vitro fertilization." (PMID 31053132, 2019).
atherosclerosis (3 papers, 2019 to 2024). A disease characterized by the build-up of fatty material and calcium deposition in the arterial wall resulting in partial or complete occlusion of the arterial lumen. "Finally, we focused on only three genes (OSM, OSMR and LIFR), while atherosclerosis is a multifactorial disease." (PMID 33959646, 2021).
glioma (3 papers, 2021 to 2024). A benign or malignant brain and spinal cord tumor that arises from glial cells (astrocytes, oligodendrocytes, ependymal cells). "Also, we observed OSM/OSMR and OSM/LIFR interaction pairs between the TAMs and MES-like cells, which was consistent with previous findings in glioma." (PMID 34805184, 2021).
ischemia (3 papers, 2017 to 2024). A hypoperfusion of the BLOOD through an organ or tissue caused by a PATHOLOGIC CONSTRICTION or obstruction of its BLOOD VESSELS, or an absence of BLOOD CIRCULATION. "The LIF/LIFR signaling pathway plays a crucial role in myocardial protection, particularly under stress conditions such as ischemia or hemodynamic overload." (PMID 39726944, 2024). "We therefore tested whether ischemia-induced activation of LIFR enhanced the expression of other protective factors by CD8+ TRLs." (PMID 35912857, 2022). "Immunohistochemical detection of LIFR in neurons incubated under normoxia showed that LIF could hypothetically trigger protective signaling in the absence of ischemia." (PMID 26746670, 2017).
lymphoma (3 papers, 2008 to 2018). A malignant (clonal) proliferation of B- lymphocytes or T- lymphocytes which involves the lymph nodes, bone marrow and/or extranodal sites. "From the repressed list of genes 4 out of 9 probes had low expression in more than 95% of the human lymphomas, whose gene names include LIFR, FABP3 and EDG1/HEXIM1 (p = 0.03)." (PMID 18535662, 2008).
mastitis (3 papers, 2015 to 2025). Inflammation of breast tissue during lactation or postpartum due to an obstructed duct or infection. "A sequence-based association study of clinical mastitis to refine previously detected QTL regions suggested NPFFR2, SLC4A4, DCK, LIFR, and EDN3 as candidate genes for mastitis susceptibility." (PMID 27014337, 2016). "The comparison between these candidate QTL regions and known genes suggested that NPFFR2, SLC4A4, DCK, LIFR, and EDN3 may be considered as candidate genes for mastitis susceptibility." (PMID 26087655, 2015). "Therefore, NPFFR2, SLC4A4, DCK, LIFR, and EDN3 are candidate genes for susceptibility to mastitis." (PMID 26087655, 2015). "Furthermore, the comparison between these candidate QTL regions and known genes suggests that NPFFR2, SLC4A4, DCK, LIFR, and EDN3 may be considered as candidate genes for mastitis susceptibility." (PMID 26087655, 2015).
stomach adenocarcinoma (3 papers, 2019 to 2025). "We analyzed mRNA expression levels of LIFR, PIK3R1 and MMP12 in cholangio carcinoma, liver hepatocellular carcinoma, pancreatic adenocarcinoma, and stomach adenocarcinoma, with the data from the TCGA." (PMID 31119098, 2019). "To examine the connection between miR-221-3p and LIFR, we utilized the starBase database and identified an inverse correlation between the expression of miR-221-3p and LIFR in breast invasive carcinoma (BRCA), stomach adenocarcinoma (STAD), and low-grade glioma (LGG)." (PMID 41272827, 2025). "Because the LIF/LIFR complex promotes an oncogenic development in several cancers, and the expression of LIF mRNA correlates with expression of FGFR4 in GC, then we saought to investigate whether the LIF regulates the expression of the FGFR4 in gastric adenocarcinoma cell lines." (PMID 37945798, 2024).
triple-negative breast carcinoma (3 papers, 2019 to 2021). An invasive breast carcinoma which is negative for expression of estrogen receptor (ER), progesterone receptor (PR), and human epidermal growth factor receptor 2 (HER2). "On the other hand, the oncogenic role of LIFR has been known in triple-negative breast cancer MBA-MD-231 cells." (PMID 32651426, 2020).
Anxiety (2 papers, 2021 to 2023). Intense feelings of nervousness, tension, or panic often arise in response to interpersonal stresses. "They found that parturient women with greater anxiety scores had lower leukemia inhibitory factor receptor (LIFR) prenatally (1 day before delivery) as well as increased IL-6 and IL-1 receptor antagonist postpartum (1 and 3 days after delivery)." (PMID 35224544, 2021).
asthma (2 papers, 2024 to 2025). "Although the authors did not investigate the mechanistic role of LIFR in asthma, the result raises the possibility that dysregulated LIFR signalling could contribute to abnormal immune cell homing in these individuals and contribute to symptoms." (PMID 39112698, 2024).
bone metastasis (2 papers, 2020 to 2021). Transfer of a neoplasm from its primary site to bones. "Evidence has suggested that higher LIFR levels are associated with favourable biological features and better outcome and loss of LIFR favours bone metastasis." (PMID 34834425, 2021).
breast invasive carcinoma (2 papers, 2023 to 2025). "However, further studies using animal models are required to determine how LIFR expression directly affects the metastatic potential of the invasive mammary carcinoma cell lines used in the current study." (PMID 37927213, 2023).
Cachexia (2 papers, 2024 to 2025). Severe weight loss, wasting of muscle, loss of appetite, and general debility related to a chronic disease. "To investigate the contribution of LIF-induced functional and metabolic changes in the liver to cachexia, we generated a mouse line with a conditional LIF knock-in allele and a conditional LIFR knockout allele (TgL/LIFRflox/flox)." (PMID 38245529, 2024). "Importantly, results from this study suggest that LIF-induced functional changes in the liver, including its metabolic changes, contribute to LIF-induced cachexia; blocking the LIF signaling in the liver by liver-specific LIFR knockout partially abolished LIF overexpression-induced cachexia in mice." (PMID 38245529, 2024).
cholangiocarcinoma (2 papers, 2015 to 2018). A carcinoma that arises from the intrahepatic biliary tree (intrahepatic cholangiocarcinoma) or from the junction, or adjacent to the junction, of the right and left hepatic ducts (hilar cholangiocarcinoma). "LIF secretion and LIFR expression were assessed in established and primary human cholangiocarcinoma cell lines." (PMID 26296968, 2015). "To investigate the role of LIF in cholangiocarcinoma, we evaluated the expression of LIF and its receptor (LIFR) in human samples." (PMID 26296968, 2015).
depression (2 papers, 2024 to 2025). "For instance, cytokine network dysregulation, including networks involving LIFR, has been reported in diseases such as depression, schizophrenia, and bipolar disorder." (PMID 38819224, 2024).
dysautonomia (2 papers, 2025). An acute or chronic disorder, affecting the sympathetic or parasympathetic nervous system. "In summary, SWS is a rare skeletal dysplasia characterised by dysautonomia and primarily caused by impaired LIFR signalling." (PMID 41211063, 2025).
Hepatic steatosis (2 papers, 2022 to 2024). Steatosis is a term used to denote lipid accumulation within hepatocytes. "Moreover, they found that LIF attenuated liver steatosis via binding to LIFR and activating the STAT3 pathway, which provided a rationale for LIF–LIFR to be a potential therapeutic target for NAFLD treatment." (PMID 36077090, 2022).
Insulin resistance (2 papers, 2024). Increased resistance towards insulin, that is, diminished effectiveness of insulin in reducing blood glucose levels. "LIFR is involved in lipolysis, adipose inflammation, hepatic triacylglycerol accumulation, and insulin resistance in mouse models." (PMID 39337639, 2024). "In this context, the changes in LIFR expression could be related to susceptibility to NAFLD and insulin resistance in patients with LADA, and the LIFR/JAK/STAT3 inflammatory pathway enhances adipocyte lipolysis." (PMID 39337639, 2024).
leukemia (2 papers, 2015 to 2025). A malignant (clonal) hematologic disorder, involving hematopoietic stem cells and characterized by the presence of primitive or atypical myeloid or lymphoid cells in the bone marrow and the blood. "LIF and its receptor, LIFR, are proteins deeply implicated in the pathogenesis of leukemia." (PMID 39781360, 2025). "Therefore, even if the expression level of LIF and LIFR themselves changes, it is possible that the association with leukemia pathogenesis may change due to the influence of other factors." (PMID 39781360, 2025). "The most distal motifs of the LIFr C-terminus can induce myeloid differentiation of leukemia cells by enhancing STAT3 phosphorylation." (PMID 26329521, 2015). "In addition to affecting LIF and LIFR, estrogen also affects the actual clinical pathogenesis of leukemia through more complex molecular actions and cellular signaling pathways." (PMID 39781360, 2025). "We explored the relationship between estrogen (E2, ESR1) and leukemia (leukemia incidence, LIF, LIFR) separately." (PMID 39781360, 2025). "Our study investigates the possible involvement of estrogen (and its receptor, ESR1) and leukemia (and its related proteins, LIF and LIFR)." (PMID 39781360, 2025).
liver fibrosis (2 papers, 2025). "In silico and pharmacological characterization of these dual modulators led to the identification of compound 2o as a first-in-class LIFR/GPBAR1 modulator that reverses liver fibrosis in vitro and in vivo." (PMID 40990291, 2025). "The identification of plant-derived LIF/LIFR antagonists providesfurther evidence of the antitumor and antifibrotic potential of Boswellia extracts and reveals bioactive metabolites forcancer and liver fibrosis therapy." (PMID 40488034, 2025).
lung adenocarcinoma (2 papers, 2022 to 2023). A carcinoma that arises from the lung and is characterized by the presence of malignant glandular epithelial cells. "The staining intensity of TNFSF14, JAM2, HGF, SPN, and LIFR in the tumors of 50 lung adenocarcinoma patients was first analyzed by immunohistochemistry and quantified according to H-scores." (PMID 36072807, 2022).
myocardial infarction (2 papers, 2021 to 2024). Gross necrosis of the myocardium, as a result of interruption of the blood supply to the area, as in coronary thrombosis. "As the ligand for LIF, LIFR expression may be significantly upregulated in certain stress or disease states, such as myocardial infarction, as a protective and reparative mechanism of the body." (PMID 39726944, 2024).
nasopharyngeal carcinoma (2 papers, 2022 to 2025). A carcinoma arising from the nasopharyngeal epithelium. "In nasopharyngeal carcinoma, MAP2K6 was associated with LIFR‐caused radioresistance." (PMID 33372369, 2022).
osteoarthritis (2 papers, 2024). A noninflammatory degenerative joint disease occurring chiefly in older persons, characterized by degeneration of the articular cartilage, hypertrophy of bone at the margins and changes in the synovial membrane. "We recognized 22 of these genes as druggable according to the DGIdb database, such as MTF1, KLC3, STAT3, LIFR, and CBFB, making them potential targets for osteoarthritis therapy." (PMID 39796139, 2024). "Although circulating inflammatory proteins may not mediate the occurrence of osteoarthritis resulting from skeletal muscle loss, this study found that high levels of CCL23, LAP-TGF-β1, and LIFR might contribute to reduce the risk of KOA, while high levels of FGF19 might increase the risk of KOA." (PMID 38811889, 2024).
peritoneal disease (2 papers, 2022 to 2025). "Here, we report that the development of peritoneal disease in our series of patients with GC is associated with a robust upregulation of the LIFR in the primary tumors." (PMID 35847866, 2022). "However, when patients with GC with or without peritoneal disease were compared, we found that LIFR expression was significantly increased in patients with PC (P-value of <0.05)." (PMID 35847866, 2022).
sarcopenia (2 papers, 2022 to 2024). Progressive decline in muscle mass due to aging which results in decreased functional capacity of muscles. "In people with sarcopenia, interval training has been shown to increase LIF and LIF receptor (LIFR) expression and STAT3 phosphorylation in gastrocnemius muscles, leading to decreased apoptosis and increased cell proliferation." (PMID 35250869, 2022).
thyroid cancer (2 papers, 2021 to 2025). "Our results indicated a suggestive association between thyroid cancer and decreased circulating levels of TNF and IFN-γ, as well as a suggestive association with increased circulating levels of LIFR." (PMID 40072746, 2025). "Our MR analysis suggests that the upregulation of LIFR levels may participate in the downstream development processes of thyroid cancer, and this conclusion needs to be further confirmed." (PMID 40072746, 2025). "Another possible reason for the insensitivity of cancer cells to sorafenib-induced ferroptosis is that LIFR expression is downregulated in a wide range of tumor types, including liver, bladder, breast, colon, kidney, lung, rectum, and thyroid cancers (TCGA data analysis)." (PMID 34921145, 2021).
autism spectrum disorder (1 paper, 2024). A spectrum of developmental disorders that includes autism, and Asperger syndrome. "For instance, alterations in cytokine levels, including those related to the LIFR pathway, have been associated with developmental abnormalities in conditions such as Autism Spectrum Disorders and Attention Deficit/Hyperactivity Disorder (ADHD)." (PMID 38819224, 2024).
bent bone dysplasia (1 paper, 2014). "STWS is a rare bent-bone dysplasia with dysautonomic manifestations that is generally caused by the autosomal recessive inheritance of a mutated LIFR gene." (PMID 24618404, 2014).
bladder cancer (1 paper, 2021). "In this study, we discovered that circLIFR, a circRNA generated from the circularization of LIFR gene, was significantly downregulated in bladder cancer." (PMID 33874956, 2021).
cardiac hypertrophy (1 paper, 2024). "Notably, murine studies have elucidated that the OSMR knockout exacerbates pressure overload-induced cardiac hypertrophy by influencing macrophages and the OSM/LIFR/STAT3 signaling pathway." (PMID 39411310, 2024).
clear cell renal cell carcinoma (1 paper, 2023). "explored the function and mechanism of action of LIFR in clear cell renal cell carcinoma (ccRCC), and found that high LIFR expression predicted a better prognosis and repressed the aggressive tumor phenotype." (PMID 36925915, 2023).
dilated cardiomyopathy (1 paper, 2018). Cardiomyopathy which is characterized by dilation and contractile dysfunction of the left and right ventricles. "Previous studies have reported that LIFR gene is one of the important differential genes in the JAK-STAT signaling pathway in people suffering from end stage dilated cardiomyopathy." (PMID 30574098, 2018).
dwarfism (1 paper, 2014). "While one symptom of STWS may be dwarfism, since LIFR-/- mice exhibit dwarfism, the short stature within the trunk region seen in STWS may, in part, be secondary to progressive scoliosis, however this would not explain the reduction in leg length." (PMID 24618404, 2014).
endometrial tumor (1 paper, 2021). "In this study using endometrial tumor tissue arrays, we identified that expression of LIF, LIFR is upregulated in EC." (PMID 34400617, 2021).
endometrioid adenocarcinoma (1 paper, 2021). An adenocarcinoma characterized by the presence of malignant glandular epithelial cells resembling endometrial cells. "IHC analysis revealed that the expression of LIF and LIFR was significantly greater in the endometrioid adenocarcinoma subtype compared to normal tissues." (PMID 34400617, 2021).
epilepsy (1 paper, 2024). A brain disorder characterized by episodes of abnormally increased neuronal discharge resulting in transient episodes of sensory or motor neurological dysfunction, or psychic dysfunction. "After a series of sensitivity analyses, Leukemia inhibitory factor receptor (LIFR) levels were excluded due to non-satisfaction of pleiotropy, and thus four inflammatory proteins were causally associated with epilepsy onset at the genetical level." (PMID 39315097, 2024).
female infertility (1 paper, 2025). Diminished or absent ability of a female to achieve conception. "Of the potential CIPs, IL2 and IL1A had the highest combined score (0.997) in male infertility, and OSM and LIFR had the highest combined score (0.999) in female infertility." (PMID 40070583, 2025).
gall bladder carcinoma (1 paper, 2021). "A study was carried out to identify the expression of LIFR, PIK3R1, and MMP- 12 in gall bladder carcinoma." (PMID 33892690, 2021).
heart failure (1 paper, 2024). Inability of the heart to pump blood at an adequate rate to meet tissue metabolic requirements. "Four of these factors were significantly causally related to the incidence of heart failure: CXCL9 and IFN-γ as promotive factors, and LIFR and UPA as potential protective factors." (PMID 39726944, 2024). "We identified CXCL9, IFN-γ, LIFR, and UPA as potential inflammatory factors associated with heart failure through forward Mendelian randomization." (PMID 39726944, 2024). "We discovered that 7 out of these 91 inflammatory factors influence heart failure, with 4 showing a significant causal relationship (CXCL9, IFN-γ, LIFR, UPA) and 3 being potentially related influencing factors (DNER, MMP-1, CD6)." (PMID 39726944, 2024).
idiopathic pulmonary fibrosis (1 paper, 2025). Idiopathic pulmonary fibrosis (IPF) is a nonneoplastic pulmonary disease that is characterized by the formation of scar tissue within the lungs in the absence of any known cause. "Interestingly, a recent report investigating novel therapeutic targets in idiopathic pulmonary fibrosis (IPF) identified Leukemia Inhibitory Factor receptor (LIFR) as an “autocrine master amplifier” of multiple upstream activators of lung fibroblasts." (PMID 40375832, 2025).
ischemic heart disease (1 paper, 2021). "Loss- and gain-of-function studies in animal models of ischemic heart disease revealed a crucial role of OSMR and LIFR activation for cardiac repair." (PMID 35008777, 2021).